GPX3 (glutathione peroxidase 3)
Diseases named in the same sentence as GPX3 in open-access papers (continued):
Sharing a sentence is not in itself a finding about the gene and the disease.
Alzheimer disease (1 paper, 2024). A progressive, neurodegenerative disease characterized by loss of function and death of nerve cells in several areas of the brain leading to loss of cognitive function such as memory and language. "Observational studies have found positive associations between GPx3 activity and Alzheimer disease (AD, the main form of dementia) likely due to higher concentrations of oxidative stress that can contribute to amyloid aggregation in extracellular space leading to GPx3 upregulation [9,]." (PMID 39270936, 2024).
Arrhythmia (1 paper, 2023). Any cardiac rhythm other than the normal sinus rhythm. "The risk of dyspnea or arrhythmia development was assessed via multivariate analysis with respect to SOD2, GPX1, GPX3 and Nrf2 genotypes (respectively)." (PMID 37373377, 2023).
asphyxia (1 paper, 2020). A state of general hypoxia and hypercapnia (abnormally elevated carbon dioxide (CO2) levels in the blood), resulting in acidosis, which affects all tissues in the body. "Similarly, in our study, the rats subjected to perinatal asphyxia expressed higher levels of GPx3 and SOD-1 in the brain." (PMID 32816128, 2020).
autism (1 paper, 2025). Persistent deficits in social interaction and communication and interaction as well as a markedly restricted repertoire of activity and interest as well as repetitive patterns of behavior. "Conversely, GSSG concentrations were significantly higher in the autism group (p < 0.01), whereas GPx3 levels were not significantly different between the groups." (PMID 40227289, 2025).
Azoospermia (1 paper, 2021). Absence of any measurable level of sperm,whereby spermatozoa cannot be observed even after centrifugation of the semen pellet. "Nevertheless, some causal links between specific selenoprotein deficiencies and phenotypes (e.g., abnormal thyroid function and deiodinase enzymes; low plasma Se and SELENOP, GPX3; azoospermia and SELENOV, GPX4, TXRND3; myopathy and SELENON) can be made." (PMID 34884733, 2021).
brain tumors (1 paper, 2023). "In our study, gpx3 was highly expressed in brain tumor tissue and also showed gender differences in the same way that gpx2 did." (PMID 37761814, 2023). "In the same way, GPx-3 also seems to be regulated by estrogens, but to our knowledge, no information is available about its role in brain tumors, although several important functions of GPx-3 have been addressed in several brain pathologies." (PMID 37761814, 2023).
breast tumors (1 paper, 2020). "In this research, we verified GPX3 mRNA expression level in 82 breast tumors and corresponding normal breast tissues by SYBR quantitative real-time RT-PCR." (PMID 33392611, 2020). "The aim of this research was to investigate the GPX3 messenger ribonucleic acid (mRNA) expression in 82 breast tumors and paired normal breast tissues by SYBR green quantitative real-time reverse transcription-polymerase chain reaction and the association with clinicopathological data." (PMID 33392611, 2020). "Previously, our data from microarray analysis (data not shown) was identified for GPX3 expression, which is one of the consistently downregulated genes in breast tumor." (PMID 33392611, 2020).
Cachexia (1 paper, 2020). Severe weight loss, wasting of muscle, loss of appetite, and general debility related to a chronic disease. "This work, in conjunction with our data, may suggest cachexia induces loss of GPX3 content, which in turn may facilitate ROS generation and subsequent pathologies." (PMID 33105841, 2020).
cancer of the oral cavity (1 paper, 2019). "Our present finding of downregulation of oxidative stress-related genes EPHX2 and GPX3, belonging to the AAM pathway, in OSCC-GB patients, is therefore notable; similar findings were also reported in cancer of the oral cavity." (PMID 31796082, 2019).
central obesity (1 paper, 2019). "On the other hand, there is a paradox with the current study that women have increased GPx-3 activity even though they have an increase in central obesity." (PMID 31817851, 2019).
chronic acute liver failure (1 paper, 2025). "In addition, in our study, we verified the target gene mRNA expression level in 40 patients with acute or chronic acute liver failure (ACHBLF) by RT-QCPR experiment and detect the methylation status of GPX3 promoter of ACHBLF patients with methylation specific PCR (MSP)." (PMID 40276677, 2025).
Cirrhosis (1 paper, 2021). A chronic disorder of the liver in which liver tissue becomes scarred and is partially replaced by regenerative nodules and fibrotic tissue resulting in loss of liver function. "Concentrations of serum SELENOP and total Se as well as GPx3 activity were determined by standardized tests and related to survival, etiology of cirrhosis/carcinoma, preoperative neutrophiles, lymphocytes, thyrotropin (TSH) and Child–Pugh and Model for End-Stage Liver Disease (MELD) scores." (PMID 33672988, 2021).
clear cell carcinomas (1 paper, 2020). "The necessity of an extracellular antioxidant such as GPx3 in clear cell carcinomas, which are associated with highly secretory phenotypes, may be of significance and needs further study." (PMID 32781581, 2020). "For example, GPx3 is highly expressed in the clear cell adenocarcinoma subtypes, including renal and ovarian clear cell carcinomas." (PMID 32781581, 2020).
diabetic cardiomyopathy (1 paper, 2025). Diabetic cardiomyopathy is a disorder of the heart muscle in people with diabetes. "While the current study focuses on elucidating TRA’s cardioprotective effects through modulation of pyroptosis and the GPX3/Nrf2 axis, future work will systematically explore its regulatory roles in lipid metabolism and insulin signaling-two central pathogenic drivers of diabetic cardiomyopathy." (PMID 40529489, 2025).
diffuse large B-cell lymphoma (1 paper, 2020). "However, the expression of GPX3 was increased in two cancer types: Lymphoid Neoplasm Diffuse Large B-cell Lymphoma (DLBC) and Thymoma (THYM)." (PMID 32316597, 2020).
disc degeneration (1 paper, 2022). "Chondrocytes 2 expressing MGP, MT1G, and GPX3 may play a role in reversing calcification and degeneration, and chondrocytes 4 expressing PTGES, TREM1, and TIMP1 may play a role in disc degeneration pain and inflammation." (PMID 35874809, 2022).
epilepsy (1 paper, 2022). A brain disorder characterized by episodes of abnormally increased neuronal discharge resulting in transient episodes of sensory or motor neurological dysfunction, or psychic dysfunction. "Some more interesting findings were noted when testing additional hypotheses related to other TE and paediatric diseases, i.e., a relatively elevated Cu and Zn status in children with epilepsy, and a general trend towards low Se, SELENOP, and GPX3 levels in phacomatoses were noted." (PMID 35745104, 2022).
fibrosis (1 paper, 2019). the formation of excess fibrous connective tissue in an organ or tissue in a reparative or reactive process. "Glutathione Peroxidase-3 (GPX3) identified in our signature has been shown to be present in the epithelial lining fluid in the bleomycin-induced fibrosis model and upregulated in IPF." (PMID 30998768, 2019).
gastritis (1 paper, 2023). Inflammation of the stomach. "For GPX3, we predicted an upstream regulatory mechanism in GC, namely DUBR/hsa-miR-502-3p/GPX3 axis, which may play a role of inhibiting in malignant transformation from gastritis to GC and play a role of promoting cancer in stepwise tumor progression." (PMID 37790850, 2023).
glaucoma (1 paper, 2023). Increased pressure in the eyeball due to obstruction of the outflow of aqueous humor. "In contrast, activation of the NRF2/ARE pathway by PLGA.EPO-R76E in glaucoma caused increased expression of Gpx 3, Prdx2, and Prdx6." (PMID 36978804, 2023).
glomerulopathies (1 paper, 2023). "As a result, a highly accurate classifier was developed (AUC = 0.99) that enables distinguishing between mild and severe glomerulopathies based on the assessment of only three urine proteins (GPX3, PLMN, and A1AT or SHBG)." (PMID 37110557, 2023).
gout (1 paper, 2019). A condition characterized by painful swelling of the joints, which is caused by deposition of urate crystals. "Sera from gout patients were analyzed to determine uric acid concentration together with two of the major extracellular antioxidant enzymes, ecSOD and Gpx3, and the TAC." (PMID 30761138, 2019).
haemorrhagic fever (1 paper, 2021). "Surprisingly, plasma concentration and activity of the selenoprotein glutathione peroxidase 3 (GPX3) were significantly higher in haemorrhagic fever with renal syndrome patients compared with controls, but this may indicate increased inflammation rather than differences in Se status." (PMID 32758306, 2021).
Hepatic steatosis (1 paper, 2024). Steatosis is a term used to denote lipid accumulation within hepatocytes. "The simultaneous upregulation of peroxidases CAT and GPX3 and the downregulation of antioxidant enzymes GSH, accompanied by elevated levels of MDA, HNE, HODE, and oxoODE, jointly indicate a close relationship between the peroxidation of FFA and hepatic steatosis (route 3)." (PMID 38837944, 2024).
hip fracture (1 paper, 2017). Traumatic or pathological injury to the hip in which the continuity of either the femoral head, femoral neck, intertrochanteric or subtrochanteric regions is broken. "A previous investigation discovered that elderly osteoporotic women with hip fractures had increased expression of GPX3, suggesting increased GPX3 antioxidative activity in bone samples." (PMID 28173844, 2017).
hyperplastic (1 paper, 2023). "Current study further validated that the expression of GPX3 in hyperplastic prostate was significantly lowered both at the transcriptional and translational levels." (PMID 37633909, 2023). "Our current study indicated that GPX3 protein was localized in both the stromal and epithelial compartments of prostate tissues with the transcription and translation levels of GPX3 were down-regulated in the hyperplastic prostate." (PMID 37633909, 2023). "In our current study, we analysed the expression of GPX3 and PCD patterns (apoptosis, autophagy and ferroptosis) in human normal and hyperplastic prostates." (PMID 37633909, 2023). "Our data suggested that GPX3 triggered G0/G1 arrest and mitochondrial-dependent apoptosis through ERK1/2 activation rather than JNK1/2 and p38 in hyperplastic prostate." (PMID 37633909, 2023).
Impaired glucose tolerance (1 paper, 2024). An abnormal resistance to glucose, i.e., a reduction in the ability to maintain glucose levels in the blood stream within normal limits following oral or intravenous administration of glucose. "According to this study, children with impaired glucose tolerance had higher GPx3 levels." (PMID 39691690, 2024).
influenza infection (1 paper, 2012). "Ultimately, as tissue recovered from influenza infection, Gpx3 started to accumulate again at the basement membranes 9 dpi (d)." (PMID 22355371, 2012). "Following influenza infection, Gpx3 became diffuse by 5–7 dpi." (PMID 22355371, 2012).
invasive carcinoma (1 paper, 2012). A carcinoma that is not confined to the epithelium, and has spread to the surrounding stroma. "Mono-allelic hypermethylation and inactivation of GPX3 in benign precursor lesions, metaplasia, and dysplasia of the esophagus has been reported; while inactivation of both alleles was detected in invasive carcinoma." (PMID 23071548, 2012).
invasive ductal carcinoma (1 paper, 2014). "Furthermore, we compared GPX3 level of expression and methylation status in aggressive phenotype inflammatory breast cancer (IBC) versus non-IBC invasive ductal carcinoma (IDC)." (PMID 24790704, 2014).
ischemia (1 paper, 2023). A hypoperfusion of the BLOOD through an organ or tissue caused by a PATHOLOGIC CONSTRICTION or obstruction of its BLOOD VESSELS, or an absence of BLOOD CIRCULATION. "Next, we utilized the C5.0 decision tree to display the criteria for splitting used in the inter-group classification: 1) if Flt1 expression is ≤ 23.029 and Gpx3 expression is ≤ 20.448, the cardiac graft belongs to either the 1h ischemia or 5h ischemia groups." (PMID 37426668, 2023).
kidney injury (1 paper, 2023). Trauma to the kidney. "This is in line with a recent study, that proposed an early GPx3-based prediction model for acute kidney injury after cardiac surgery." (PMID 38063975, 2023).
kidney stones (1 paper, 2020). "Based on the results of the data set analysis, PTGS1, GPX3 and MMD were also highly expressed in the samples of kidney stones." (PMID 33277533, 2020). "Some previous studies have shown that LCN2, PTGS1, GPX3 and MMD may play a role in the development and progression of kidney stones." (PMID 33277533, 2020).
liver disease (1 paper, 2025). "Notably, the Kyoto Encyclopedia of Genes and Genomes (KEGG) pathway analysis further identified GPX3’s involvement in “PPAR signaling” (hsa03320) and “Fatty acid degradation” (hsa00071), pathways directly linked to lipid dysregulation observed in advanced liver disease." (PMID 40276677, 2025).
liver failure (1 paper, 2025). A liver disease characterized by the liver losing or has lost all of its function. "In this study, we utilized bioinformatics methods to analyze multiple datasets, confirming the expression changes of GPX3 in liver failure patients and evaluating its potential as a diagnostic biomarker through ROC curve analysis." (PMID 40276677, 2025). "While elevated GPX3 levels are linked to diverse pathologies, its role in liver failure (LF) remains underexplored." (PMID 40276677, 2025). "Our identification of GPX3 as a potential diagnostic biomarker (AUC = 0.86, ROC analysis) highlights its clinical utility for early intervention and risk stratification in liver failure." (PMID 40276677, 2025). "The superior diagnostic performance of GPX3 (AUC = 0.86 vs MELD score AUC = 0.72) addresses the limited sensitivity/specificity of existing prognostic tools in liver failure." (PMID 40276677, 2025). "In conclusion, GPX3 is a promising diagnostic biomarker for liver failure." (PMID 40276677, 2025). "The results demonstrate that GPX3 drives pathogenic mechanisms in liver failure through oxidative stress-related pathways (e.g., collagen cross-linking, extracellular matrix remodeling) and immune dysregulation (e.g., macrophage activation, PD-1/CTLA-4 signaling)." (PMID 40276677, 2025). "Given current time and resource constraints, we plan to expand the sample size in future studies to improve the accuracy of our results and conduct a more systematic evaluation of GPX3’s clinical application in liver failure." (PMID 40276677, 2025). "This spatial context supports GPX3’s role in liver failure pathogenesis through redox and immune pathways." (PMID 40276677, 2025). "Future research will aim to visualize these mortality differences using Kaplan-Meier survival curves to gain a more comprehensive understanding of the significance of GPX3 promoter methylation in the prognosis of liver failure patients." (PMID 40276677, 2025). "The integration of these findings with GO/KEGG results supports GPX3’s dual role in mitigating oxidative damage and regulating immune dysregulation, highlighting its potential as a therapeutic target for halting hepatic fibrosis progression in liver failure." (PMID 40276677, 2025). "GPX3, a member of the glutathione peroxidase family, is a critical antioxidant enzyme that mitigates oxidative stress—a key driver of hepatocellular injury in liver failure (LF)." (PMID 40276677, 2025). "GPX3 upregulation in liver failure specimens (logFC = 2.1, adj." (PMID 40276677, 2025). "Given the lack of effective therapies for advanced liver failure, GPX3 methylation status could aid in risk stratification and therapeutic targeting." (PMID 40276677, 2025). "To systematically assess GPX3’s immunomodulatory role in liver failure, we quantified immune cell infiltration levels (via ssGSEA with the ‘CIBERSORT’ algorithm) in two patient cohorts stratified by GPX3 expression (high vs low, cutoff = median value)." (PMID 40276677, 2025). "GPX3 downregulation exacerbates oxidative stress-mediated collagen degradation, driving pathological ECM remodeling and fibrosis progression in liver failure." (PMID 40276677, 2025).
liver fibrosis (1 paper, 2023). "Consequently, CR led to an elevation of proteomic markers associated with liver inflammation (e.g., GSTP1, GPX3) or liver fibrosis (e.g., TGFBI, TNC), and therefore, rather compromised liver health instead of improving it." (PMID 37630850, 2023).
meningioma (1 paper, 2025). A generally slow growing tumor attached to the dura mater. "Oxidative stress-related genes such as AOX1, FOXM1, GPX3, PRNP, and SEPP1 were differentially expressed between high- and low-grade meningiomas." (PMID 41050085, 2025). "This study further experimentally validated the key oxidative stress-related genes: AOX1, FOXM1, GPX3, PRNP, and SEPP1 in human meningeal cells (HMC) and two meningioma cells (CH-157MN and IOMM-Lee)." (PMID 41050085, 2025). "It was noted that most of the oxidative stress-related genes presented differential expression between high-grade and low-grade meningiomas, especially AOX1, FOXM1, GPX3, PRNP, and SEPP1." (PMID 41050085, 2025).
metastatic cancers (1 paper, 2021). A carcinoma which has spread from the original site of growth to another anatomic site. "Low GPX activity was found associated with enhanced lipid peroxidation in metastatic cancers, indicating that loss of GPX3 may promote systemic oxidative stress." (PMID 34660806, 2021).
metastatic disease (1 paper, 2020). "Proteomics analysis on the cerebrospinal fluids of the extranodal NK-/T-cell lymphomas patients has identified GPX3 as a predictor of metastatic disease." (PMID 32763516, 2020).
myocardial infarction (1 paper, 2025). Gross necrosis of the myocardium, as a result of interruption of the blood supply to the area, as in coronary thrombosis. "Conclusively, these multifaceted protective properties of GPX3 enhance cardiac repair and functional recovery after myocardial infarction, further providing valuable insights for developing novel therapeutic strategies in clinical settings." (PMID 39900557, 2025). "Despite these findings, the specific role of GPX3 in cardiac diseases, particularly in myocardial infarction, remains underexplored and warrants further investigation." (PMID 39900557, 2025). "In this study, we report a novel discovery that GPX3 levels are significantly elevated in both myocardial infarction tissues and plasma." (PMID 39900557, 2025). "Collectively, these findings suggested that GPX3 mediates Hif1α expression through LSD1, thereby enhancing cardiomyocyte survival and facilitating cardiac repair post‐myocardial infarction." (PMID 39900557, 2025). "Moreover, given that GPX3 expression tends to decline with age and the onset of an unhealthy lifestyle, this reduction may contribute to the observed poorer prognosis following myocardial infarction in older individuals." (PMID 39900557, 2025).
ovulation (1 paper, 2023). The release of a mature ovum/oocyte from an ovary. "Compared to the single model, the combined model of clinical (Ovulation dysfunction) and specific genes (GAST, GPX3, THBS2) was more accurate to predict live birth for IVF-ET patients." (PMID 37777726, 2023).
Parkinson disease (1 paper, 2021). A progressive degenerative disorder of the central nervous system characterized by loss of dopamine producing neurons in the substantia nigra and the presence of Lewy bodies in the substantia nigra and locus coeruleus. "In a recent study, using two microarray data, viz, GSE99039 (the dataset we used in this study) and GSE72267 as the training set, GPX3 was identified as a DEG for Parkinson’s disease as well." (PMID 33596182, 2021).